SIRT2 (sirtuin 2)
Diseases named in the same sentence as SIRT2 in open-access papers (continued):
Sharing a sentence is not in itself a finding about the gene and the disease.
Stroke (11 papers, 2015 to 2024). Sudden impairment of blood flow to a part of the brain due to occlusion or rupture of an artery to the brain. "Photothrombotic stroke caused a sharp increase in the level of SIRT2 in the cytoplasmic fraction of the penumbra after 4 and 24 h." (PMID 35574497, 2022). "Photothrombotic stroke caused a sharp increase in SIRT2 levels in the cytoplasmic fraction of the penumbra neurons." (PMID 35574497, 2022). "Recently, a number of studies have shown that SIRT2, may have an association with stroke." (PMID 37684620, 2023). "Serum SIRT2 levels were also positively correlated with NIH Stroke Score, tumor necrosis factor-α, IL-6 and IL-17." (PMID 39001884, 2024). "Previous studies have shown that microglial SIRT2 expression is upregulated during stroke, which leads to inhibition of the anti-inflammatory function of infiltrating regulatory T cells." (PMID 39001884, 2024). "Recent studies have shown that SIRT2 is involved in the pathogenesis of neurological disorders, including neurodegenerative diseases, stroke, and tumors of the central nervous system." (PMID 37684620, 2023). "In animal models of stroke, SIRT2 inhibition showed neuroprotective effects, which is directionally consistent with our findings." (PMID 37794467, 2023). "We studied the effect of SIRT1 and SIRT2 inhibitors on the apoptosis of peri-infarct area cells and the infarction volume in the brain of mice, developing 4 or 7 days after photothrombotic stroke." (PMID 35574497, 2022). "After a stroke, the SIRT2 protein is significantly expressed in myelin-rich brain regions, and Sirt2 knockout mice displayed reduced neurological impairments in MCAO models with various occlusion times." (PMID 35574497, 2022). "Another study showed that the anti-inflammatory effect of Treg cells was weakened by SIRT2 on pro-inflammatory macrophages, which indirectly impacted the process of stroke in the model of middle cerebral artery occlusion." (PMID 35813508, 2022). "Inhibition of SIRT2 by AK-7 rescued neurological function and decreased stroke volume via p38 activation." (PMID 34108853, 2021). "SIRT2 impairs the anti-inflammatory effect of Treg cells and indirectly impacts the process of stroke in the MCAO model." (PMID 34108853, 2021). "In brain injury and stroke, SIRT2 modulators usually take their effect through regulating neuroinflammation and autophagy, but a definite conclusion on their efficacy has not been reached, mainly due to lack of substantial data." (PMID 34108853, 2021). "Our studies also show that activation of SIRT1 during the acute period of stroke does not have an unconditioned neuroprotective effect, while SIRT2 is associated with damage to penumbra cells." (PMID 35574497, 2022). "Likewise, inflammatory parameters were comparable in SIRT2+/+ and SIRT2−/− mice with experimental stroke and Mycobacterium tuberculosis infection." (PMID 28894448, 2017). "Moreover, inhibiting SIRT2 in serum exosomes could potentially be a therapeutic strategy to protect against the harmful effects of stroke." (PMID 37684620, 2023). "Thus, SIRT2 also performs contradictory functions in stroke." (PMID 34680562, 2021). "Finally, in an experimental stroke model, SIRT2 deficiency preserved neurological functions without affecting inflammatory parameters." (PMID 28894448, 2017). "In our previous study, SIRT2 inhibitor AK7 was found to decrease the infarct area, and improved behavior in mouse stroke models by activating the p38 Mitogen-Activated Protein Kinase (MAPK) signal pathway." (PMID 37684620, 2023). "We observed a positive correlation between enhanced exosomes SIRT2 level and both NIHSS and mRS scores, which are commonly used metrics for assessing stroke severity and functional disability." (PMID 37684620, 2023). "Overall, these findings provide valuable insights into the role of serum exosome SIRT2 in the pathogenesis of AIS and highlights the importance of identifying novel biomarkers for improving diagnosis and treatment of stroke." (PMID 37684620, 2023).
Stroke (continued). "However, the ability of SIRT1 and SIRT2 to translocate between cell compartments in response to ischemia and participate in the acetylation of both nuclear and cytoplasmic proteins indicates a more complex role of these deacetylases in the pathogenesis of stroke." (PMID 35574497, 2022). "We studied the effects of photothrombotic stroke (PTS) on the expression and localization of sirtuins SIRT1 and SIRT2 in neurons and astrocytes of the penumbra and tested the activity of their selective and non-selective inhibitors." (PMID 35574497, 2022). "More research is needed to elucidate the mechanisms of the synergistic effects of SIRT1, SIRT2, and SIRT3 on the protection and death of penumbra cells in stroke." (PMID 35574497, 2022). "Recent studies demonstrated that SIRT2 participates in even more pathological processes such as frontotemporal dementia (FTD), stroke, and brain injury." (PMID 34108853, 2021). "Moreover, treatment with AK7 was not beneficial in mouse model of stroke, where a therapeutic role of SIRT2 inhibition has been proposed but remains controversial." (PMID 25608039, 2015). "Twenty proteins were associated with outcome in univariable models after correction for multiple testing (FDR < 0.05), and for 5 the association was independent of clinical variables, including stroke severity (TNFSF14 [LIGHT], OSM, SIRT2, STAMBP, and 4E-BP1)." (PMID 37794467, 2023).
Hepatic fibrosis (9 papers, 2021 to 2024). The presence of excessive fibrous connective tissue in the liver. "SIRT2 deficiency mice are less susceptible to the development of carbon tetrachloride (CCl4)/TAA-induced liver fibrosis." (PMID 39226168, 2024). "Studies have shown that SIRT2 is expressed in human fibrotic tissue and over-expressed SIRT2 promotes liver fibrosis." (PMID 39226168, 2024). "In conclusion, SIRT2 can participate in the pathogenesis of liver fibrosis during aging by activating HSC, promoting HBV replication and regulating lipid metabolism." (PMID 39226168, 2024). "Research has found that the SIRT2/ERK/c-MYC axis plays a crucial role in promoting liver fibrosis, and SIRT2 inhibitors are a potential new strategy for treating liver fibrosis and cirrhosis." (PMID 39226168, 2024). "Current investigations of SIRT2 and fibrosis development in the aging process involve liver fibrosis, kidney fibrosis, cardiovascular fibrosis, and pulmonary fibrosis." (PMID 39226168, 2024). "Because non-alcoholic fatty liver disease is an important cause of liver cirrhosis and SIRT2 can be regulated through different signaling pathways of lipid metabolism, SIRT2 is also important for liver fibrosis." (PMID 39226168, 2024). "A study also showed that the deficiency of Sirt2 alleviated hepatic fibrosis in thioacetamide (TAA) and carbon tetrachloride (CCl4) induced Hepatic fibrosis." (PMID 38993557, 2024). "SIRT2, on the other hand, can aggravate liver injury and its inhibition has been found to decrease hepatic fibrosis." (PMID 38993557, 2024). "To determine the roles of SIRT2 expression in human liver fibrosis, we examined liver specimens from four stages, from healthy to NASH progression: healthy controls, patients with mild fibrosis (F0, F1), moderate fibrosis (F2), and advanced fibrosis (F3)." (PMID 37240315, 2023). "Accumulating previous studies reported that SIRT2 plays different roles in the fibrosis of various organs, including cardiac fibrosis, liver fibrosis, pancreatic fibrosis, pulmonary fibrosis, and renal fibrosis." (PMID 34642310, 2021). "SIRT2-specific inhibitors have also been shown to reverse liver fibrosis, which indicates targeting SIRT2 may become a potential strategy." (PMID 39226168, 2024). "However, some reports have suggested that SIRT2 inhibition represses fibrogenic genes in HSCs to prevent hepatic fibrosis." (PMID 38993557, 2024). "SIRT2 inhibition, on the other hand, has been shown to alleviate organ fibrosis, but its role in liver fibrosis remains unclear." (PMID 38993557, 2024). "However, another study suggested that SIRT2 inhibition suppressed carbon tetrachloride- or thioacetamide-induced hepatic fibrosis." (PMID 39871927, 2022). "A pro-fibrotic function of Sirt2 has been documented in hepatic fibrosis." (PMID 34925016, 2021). "Similarly, specific deletion of Sirt2 in hepatocyte aggravated CCl4-induced hepatic fibrosis." (PMID 37777567, 2023). "However, there are conflicting reports on the roles of SIRT2 in liver fibrosis." (PMID 34642310, 2021). "In the current study, we found that SIRT2 expression were reduced in the liver of CCL4-induced hepatic fibrosis, and specific deletion of Sirt2 in hepatocyte aggravated CCl4-induced hepatic fibrosis and upregulated TGF-β regulated genes expression." (PMID 37777567, 2023). "Because NIAAA mice do not develop liver fibrosis, the more ideal mouse model may be helpful to further identify the roles of SIRT2 in alcoholic liver fibrosis." (PMID 34642310, 2021).
Listeria monocytogenes infection (9 papers, 2015 to 2023). "During Listeria monocytogenes infection, the host deacetylase sirtuin 2 (SIRT2) translocates to the nucleus, causing deacetylation of H3K18, thereby facilitating infection by repressing a specific set of genes." (PMID 28594938, 2017). "InlB has been reported to support Listeria infection in epithelial cells by modulating transcriptional host cell responses via SIRT2-mediated histone H3K18 deacetylation." (PMID 36656016, 2023). "In Listeria monocytogenes infection, SIRT2 translocates to the nucleus and deacetylates H3K18, which associates with a subset of host genes that are crucial during the bacterial life cycle." (PMID 36719240, 2023). "In case of Listeria infection, SIRT2 translocation is mediated by PI3K/AKT signaling pathway in an InlB dependent manner." (PMID 30452468, 2018). "Recently, Sirt2 was shown to prevent the development of inflammatory processes and its expression favors acute Listeria monocytogenes infection." (PMID 26135889, 2015). "Similarly, SIRT-2−/− mice exerted resistance against Listeria monocytogenes infection due to impaired H3 histone lysine 18 (H3K18) deacetylation that is mediated by SIRT-2." (PMID 34485381, 2021). "Interestingly, cells silenced for IPO7 or all three importins did not undergo H3K18 deacetylation suggesting that IPO7 is specifically required to allow SIRT2 to carry out nuclear functions in response to Listeria monocytogenes infection." (PMID 32042025, 2020). "To examine whether the identified importins played a role in permitting the nuclear functions of SIRT2, we tested whether RNAi effected H3K18 deacetylation during Listeria monocytogenes infection." (PMID 32042025, 2020).
renal fibrosis (9 papers, 2021 to 2024). A final common manifestation of a wide variety of chronic kidney diseases characterized by glomerulosclerosis and tubulointerstitial fibrosis. "A potential interaction between SIRT2 and the top 20 genes associated with renal fibrosis was generated by the STRING database, a predictive web interface for gene functions." (PMID 37777567, 2023). "SIRT2 regulates renal fibrosis by affecting acute renal injury, tubulointerstitial fibrosis, and fibroblast activation." (PMID 39226168, 2024). "Research has established the role of Sirt2 in driving inflammation and renal fibrosis, leading to the development of Sirt2 inhibitors, including AK-1 and AGK2." (PMID 39911234, 2024). "In the kidney, SIRT2 regulates renal fibrosis by affecting acute kidney injury, renal tubulointerstitial fibrosis, and fibroblast activation." (PMID 39226168, 2024). "Sirt2 activity is implicated in the induction and expansion of renal fibroblast activity, in contrast, suppression of Sirt2 attenuates renal fibrosis progression and presents a promising therapeutic strategy for managing CKD." (PMID 39911234, 2024). "SIRT2 promotes renal fibrosis by mediating TIF and fibroblast activation, making SIRT2 inhibitors promising therapeutic agents." (PMID 39226168, 2024). "Studies have confirmed the involvement of Sirt2 in renal fibrosis and inflammation, and inhibitors of Sirt2, such as AGK2, and AK-1, have been developed." (PMID 38347622, 2024). "Consistently, renal tubule epithelial cell-specific Sirt2 overexpression alleviated renal fibrosis in UUO and uIRI mice." (PMID 37777567, 2023). "TXNDC5 (endoplasmic reticulum protein) and SIRT2 (sirtuin 2) both promote renal fibrosis through upregulation of TGF-β1 expression in kidney fibroblasts." (PMID 36768457, 2023). "Overall, these data suggested that SMAD2 and SMAD3 are important targets of SIRT2 against renal fibrosis." (PMID 37777567, 2023). "In kidneys that are obstructed, specific deletion of Sirt2 in renal tubule epithelial cells (TEC) has been shown to aggravate renal fibrosis, while renal tubule specific overexpression of Sirt2 has been shown to ameliorate renal fibrosis." (PMID 37777567, 2023). "Consistent with the anti-fibrotic effect of SIRT2 observed in vitro, targeted deletion of SIRT2 in renal tubule epithelial cells aggravated renal fibrosis induced by UUO." (PMID 37777567, 2023). "Taken together, these results suggest that SIRT2 overexpression in renal tubular epithelial cells alleviates the development of renal fibrosis in UUO and uIRI mice." (PMID 37777567, 2023). "In the present study, we have demonstrated that SIRT2, an NAD+-dependent deacetylase, is increased in the renal tubules and is critical to the pathogenic pathway of renal fibrosis." (PMID 37777567, 2023). "Our investigations have revealed that SIRT2 suppresses renal fibrosis by inhibiting pro-fibrotic TGF-β signaling through the promotion of deacetylation of SMAD2 and SMAD3." (PMID 37777567, 2023). "The activity of Sirt2 contributes to the activation and proliferation of renal fibroblasts, while blocking Sirt2 activation attenuates the development of renal fibrosis and may have therapeutic potential for the treatment of CKD." (PMID 38347622, 2024). "In addition, we sought to identify a new role for SIRT2 in regulating the TGF-β/SMAD signaling pathway to suppress renal fibrosis." (PMID 37777567, 2023). "Above all, these findings uncover the causal role of SIRT2 in the progression of renal fibrosis through the control of TGF-β/SMAD signaling and suggest that SIRT2 has the potential to be an effective therapeutic approach for both prevention and treatment of renal fibrosis as part of CKD." (PMID 37777567, 2023). "While in hepatic and renal fibrosis, Sirt2 demonstrated the pro-fibrogenesis characteristics, blocking Sirt2 inhibited the activation of hepatic stellate cells and renal interstitial fibroblasts, and suppressed hepatic and renal fibrosis." (PMID 34925016, 2021).
renal fibrosis (continued). "Thus, specific overexpression of SIRT2 in renal tubule epithelial cells may alleviate and restrain UUO- and uIRI-caused renal fibrosis." (PMID 37777567, 2023). "Overexpression of SIRT2 in TECs can restrain the signaling of TGF-β/SMAD and cease the tissue’s excessive response, thus inhibiting renal fibrosis." (PMID 37777567, 2023). "Immunohistochemistry and immunoblotting also showed substantial downregulation of SIRT2 protein in fibrotic mouse kidney tissues induced by UUO and uIRI, both of which are characterized by substantial renal fibrosis." (PMID 37777567, 2023). "The class III HDAC family members currently thought to be associated with the development of renal fibrosis mainly include SIRT1 and SIRT2; there is no consensus on the role of SIRT1 in renal fibrosis." (PMID 36148005, 2022). "Although the expression of SIRT2 has been detected in the renal tubules of disease-free human and mouse kidneys, the role of SIRT2 in proximal tubular epithelial cells (TECs) in renal fibrosis has not been documented." (PMID 37777567, 2023). "In addition, SMAD2 and SMAD3 knockout augmented the production of inflammatory factor (TNFα and IL-6), while SIRT2-mediated NLRP3 deacetylation protects against inflammation, indicating SIRT2 may be a more attractive target to improving renal fibrosis." (PMID 37777567, 2023).
atherosclerosis (8 papers, 2020 to 2025). A disease characterized by the build-up of fatty material and calcium deposition in the arterial wall resulting in partial or complete occlusion of the arterial lumen. "This role of SIRT2 could prevent obesity and metabolic diseases such as diabetes, which are risk factors in atherosclerosis development." (PMID 33614337, 2021). "Moreover, increased miR-140-5p elevated ROS levels causing oxidative stress by Nrf2/Sirt2/Keap1/HO-1 pathway in mice with atherosclerosis." (PMID 35011574, 2021). "Our previous study indicated that Sirt2 can reduce atherosclerosis by regulating the phenotype of macrophages." (PMID 40523615, 2025). "Previous studies have shown that miR‐140‐5p can enhance oxidative stress by directly targeting NRF2 and SIRT2 mRNAs, thereby exacerbating atherosclerosis." (PMID 41171011, 2025). "SIRT2 also functions in the signaling pathway through which other molecules affect atherosclerosis." (PMID 35677446, 2022). "Notably, microRNA-140-5p, an endogenous small non-coding RNAs, was found to relieve hypertension and oxidative stress in atherosclerosis by functioning on SIRT2 and Nrf2." (PMID 35677446, 2022). "SIRT2 has been consistently shown to protect against VC, especially atherosclerosis." (PMID 35677446, 2022). "This proved that SIRT2 can transform macrophages in HUVEC from M1 type to M2 type, thereby stabilizing plaque in atherosclerosis." (PMID 34028177, 2021). "Compared with SIRT1, the influence of SIRT2 on VC has not been thoroughly investigated; however, in recent years, several studies on SIRT2 and atherosclerosis have been reported." (PMID 35677446, 2022).
liver cancer (8 papers, 2017 to 2026). An epithelial or non-epithelial malignant neoplasm that arises from the liver. "We found that SIRT2 can upregulate IGFBP1 expression and subsequently activate the PI3K/AKT/mTOR signalling pathway and that IGFBP1 is essential for the tumour-promoting function of SIRT2 in liver cancer." (PMID 42009830, 2026). "In this study, we thoroughly investigated the function and regulatory mechanism of SIRT2 in the tumorigenesis of liver cancer and found that SIRT2 is highly expressed in liver cancer tissues and is distributed mainly in the cytoplasm of liver cancer cells." (PMID 42009830, 2026). "SIRT2 overexpression in liver cancer cells leads to overexpression of the β-catenin signaling pathway, which enhances the epithelial–mesenchymal transition (EMT)." (PMID 41304967, 2025). "For instance, SIRT2 can encourage the progression of liver cancer through the activation of Akt and subsequent inhibition of epithelial-mesenchymal transition GSK-3, which leads to the raising of the β-catenin protein." (PMID 36750593, 2023). "In addition, there is a report showing that SIRT2 can promote liver cancer metastasis by regulating EMT progression." (PMID 30584257, 2018). "Additionally, SIRT2 increases the activity of Phosphoenolpyruvate Carboxykinase 1 (PEPCK1) and Glutaminase (GLS), which promote the metabolism of glycolysis and inhibit the E-cadherin pathway, which promotes the invasion of liver cancer cells." (PMID 36750593, 2023).
amyotrophic lateral sclerosis (7 papers, 2015 to 2024). Amyotrophic lateral sclerosis (ALS) is a neurodegenerative disease characterized by progressive muscular paralysis reflecting degeneration of motor neurons in the primary motor cortex, corticospinal tracts, brainstem and spinal cord. "The levels of SIRT2 increase with aging, and we previously showed that pharmacological inhibition of this sirtuin is protective in cellular, Drosophila, and mouse models of PD but not in models of amyotrophic lateral sclerosis." (PMID 28257421, 2017).